MTHFD2 (methylenetetrahydrofolate dehydrogenase (NADP+ dependent) 2, methenyltetrahydrofolate cyclohydrolase)
Diseases named in the same sentence as MTHFD2 in open-access papers (continued):
Sharing a sentence is not in itself a finding about the gene and the disease.
tumor (continued). "Previous studies and our experiments have proven the high expression and tumor-promoting effect of MTHFD2 in NSCLC." (PMID 36051358, 2022). "It is clearly seen that the tumor tissues have higher MTHFD2 expressions than normal tissues, confirming that the MTHFD2 gene expression is elevated in BLCA (Table.S1_F)." (PMID 35581573, 2022). "In this study, we characterized the gene and protein expression of MTHFD2 in tumor tissues, and investigated the correlation between its transcriptional levels and clinical prognosis in patients with LUAD using TCGA database." (PMID 35790743, 2022). "Collectively, MTHFD2 promotes functional PD-L1 at least partially through upregulating its transcriptional activity; and this role of MTHFD2 is necessary for tumor cells to evade effector T cell cytotoxicity." (PMID 33782411, 2021). "Meanwhile, MTHFD2 promotes PD-L1-mediated tumor immunoresistance through the folate cycle-HBP metabolic pathway and the UDP-GlcNAc-O-GlcNAcylation-MYC-PD-L1 signaling pathway." (PMID 33782411, 2021). "Targeting 1C metabolism has the potential to inhibit malignant tumor behaviors, as shown by the effects of drugs targeting Mthfd2, Shmt2, and Mettl3." (PMID 34298902, 2021). "Methylenetetrahydrofolate dehydrogenase 2 (MTHFD2), which is known as a mitochondrial one‐carbon metabolism enzyme, is reported to be up‐regulated in various tumours." (PMID 34121323, 2021). "The shRNA targeting mouse MTHFD2 suppressed tumor growth moderately in nude mice, but dramatically (around 80%) in C57 mice, which contain mature lymphocytes." (PMID 33782411, 2021). "Through functional screening, we found that folate cycle enzymes, especially MTHFD2, enable tumor cells to become more tolerant to effector T cells." (PMID 33782411, 2021). "MTHFD2 KD suppressed both basal and IFN-γ-elevated PD-L1, indicating high basal level of tumor MTHFD2 plus IFN-γ-elevated MTHFD2 both contribute to PD-L1 expression during IFN-γ stimulation." (PMID 33782411, 2021). "Taken together, these data indicate that the PD-L1-up-regulatory effect of MTHFD2 is necessary for tumor development." (PMID 33782411, 2021). "Here we perform a functional screen of metabolic genes that rescue tumour cells from effector T cell cytotoxicity, and identify the embryo- and tumour-specific folate cycle enzyme methylenetetrahydrofolate dehydrogenase 2 (MTHFD2)." (PMID 33782411, 2021). "Further, to examine the in vivo effect of MTHFD2 on tumor growth, we injected MTHFD2-knockdown cell lines in mice, which revealed significantly decreased tumor size compared to its parental counterpart." (PMID 32759461, 2020). "Most tumor samples with highly expressed MTHFD2 exhibited the upregulated protein levels of SIRT3 compared with adjacent nontumor tissues (P < 0.01)." (PMID 32811824, 2020). "Of these 15 pairs of samples, MTHFD2 protein was significantly increased in tumor samples, however the acetylated K88 in MTHFD2 was reversibly downregulated in all tumor samples (P < 0.0001)." (PMID 32811824, 2020). "More recently, MTHFD2 was reported to promoted metabolic reprogramming and tumor progression by forming a positive feedforward loop with HIF-2α." (PMID 32411609, 2020). "Necrosis was noted in the core of both tumor types; however, necrosis was higher in the MTHFD2 knockdown tumors." (PMID 33262939, 2020). "The first synthetic MTHFD2 inhibitor LY345899 has shown potent anti-tumor activity in CRC while the research and development of inhibitors with higher affinity and selectivity is still ongoing." (PMID 32411609, 2020). "Further studies are warranted to elucidate the molecular mechanisms for the tumor promoting role of MTHFD2 in HNSCC." (PMID 32933024, 2020). "Conclusively, the suppressed levels of MTHFD2 is essential for cellular metabolic reprogramming leading to inhibited LCa growth and tumor aggressiveness." (PMID 32759461, 2020).
tumor (continued). "To verify the tumor-promoting effect of MTHFD2 on GC, we first examined the expression of MTHFD2 in GC tissues and cell lines." (PMID 33168819, 2020). "Targeting MTHFD2 is a promising approach to design innovative therapeutic drugs for tumor treatment." (PMID 32811824, 2020). "In accordance with our above results, Western blot analysis revealed that CCNA2, MCM7 and SKP2 expression were decreased in the MTHFD2 knockdown tumour tissues compared with shCtrl tumour tissues." (PMID 31778025, 2020). "The generation of NADPH by MTHFD2 is able to overcome oxidative stress and maintain redox homeostasis, which are critical steps for tumor progression." (PMID 32811824, 2020). "The expression level of MTHFD2 was significantly overexpressed in tumor tissues compared to the normal controls in both GSE6631 and TCGA HNSCC cohort." (PMID 32933024, 2020). "We found that both cell lines formed tumor spheres and that shRNA-mediated knockdown of MTHFD2 significantly inhibited tumor sphere formation." (PMID 30532069, 2019). "We also performed an in vitro limiting dilution assay and confirmed that knockdown of MTHFD2 significantly inhibited tumor sphere formation." (PMID 30532069, 2019). "Within the mitochondrial folate pathway, MTHFD2 is of special interest, because MTHFD2 was one of the most consistently overexpressed mRNAs genome-wide across 19 different tumor types." (PMID 28210221, 2017). "We further confirm presence of MTHFD2 in the nucleus in tumor samples and future experiments will address the clinical relevance of nuclear MTFHD2." (PMID 26461067, 2015). "Targeting MTHFD2 may represent a dual-action strategy to suppress tumor growth and reprogram the tumor immune microenvironment." (PMID 41752156, 2026). "MTHFD2 acts as an important enzyme in 1C metabolism, which provides important metabolites for cell survival and proliferation, especially rapidly proliferating tumor cells." (PMID 40280919, 2025). "Furthermore, genetic or pharmacological inhibition of MTHFD2 reduces tumor burden in both GC cell lines and patient-derived xenograft-based models." (PMID 38723197, 2024). "Moreover, genetic or pharmacological inhibition of MTHFD2 reduces tumor burden in both tumor cell lines and patient-derived xenograft-based models." (PMID 38723197, 2024). "Moreover, genetic or pharmacological inhibition of MTHFD2 reduces tumor burden in both tumor cell lines and PDX-based models." (PMID 38723197, 2024). "Furthermore, by in vivo and in vitro experiments, MTHFD2 knockdown reduced tumor size and impaired cell proliferation, migration, and invasion." (PMID 38422037, 2024). "Therefore, the critical role of MTHFD2 in protecting GC cells from oxidative stress makes it highly expressed in tumor tissue." (PMID 38723197, 2024). "MTHFD2 is an embryo‐ and tumor‐specific folate cycle enzyme." (PMID 38483955, 2024). "Several MTHFD1 and MTHFD2 inhibitors have been developed and shown to limit tumour development." (PMID 38698089, 2024). "As growing evidence indicates the fundamental roles of redox regulation in tumor growth, we hypothesized that MTHFD2-mediated NADPH homeostasis may promote GC tumorigenesis." (PMID 38723197, 2024). "The high-expression of miR-504-3p is associated with good prognosis in AML patients and may serve as a tumor suppressor by targeting MTHFD2." (PMID 37147729, 2023). "These tumor-related biological characteristics may be attributed to the MTHFD2-related promotion of intracellular DNA synthesis, which may reduce intracellular oxidation levels and cell death." (PMID 36726381, 2023). "Furthermore, the enrichment scores of all immunotherapy predicted pathways and the expression of effector genes for most anti-tumor immune cells were elevated in patients with high MTHFD2 expression." (PMID 38130721, 2023).
tumor (continued). "To verify whether MTHFD2 was correlated with immune infiltration levels, we assessed the correlation of MTHFD2 expression with tumour purity and diverse immune cells infiltration levels from TIMER database." (PMID 37480214, 2023). "Recently, accumulating studies have indicated the important role of MTHFD2 in tumor progression." (PMID 37484807, 2023). "Based on the HPA database, the MTHFD2 was also higher in tumor tissues at the protein level." (PMID 37484807, 2023). "Furthermore, a T24 xenograft tumour model was established in nude mice to demonstrate the functions of MTHFD2 in vivo." (PMID 37480214, 2023). "Furthermore, we undertook immunohistochemistry staining for MTHFD2 in the tumour and adjacent normal tissues of eight patients with BC." (PMID 37480214, 2023). "Enrichment analyses showed that MTHFD2 is involved in various tumor-related biological processes." (PMID 36726381, 2023). "Thus, our data suggest that MTHFD2 activity is essential for proper and correct completion of DNA replication specifically in tumor cells." (PMID 35228749, 2022). "Remarkably, tumor cells from solid LUADs upregulate energy and substance metabolic activities, particularly the folate-mediated one-carbon metabolism and the key gene MTHFD2, which could serve as a potential therapeutic target." (PMID 36138435, 2022). "Moreover, specific inhibition of MTHFD2 functions by siRNA or a chemical compound, improved anti-tumor sensitivities induced by pemetrexed in LUAD." (PMID 35790743, 2022). "Moreover, bioinformatics studies showed higher transcriptional levels of MTHFD2 were present in tumor tissues and correlated with poor survival rate in patients with LUAD." (PMID 35790743, 2022). "In contrast, knockdown of MTHFD2 expression reduced xenograft tumor growth." (PMID 35873461, 2022). "Our following study will continue to figure out if MTHFD2 could drive tumor cell proliferation, migration, and cycle progression and inhibit cell apoptosis in UCB, just as in other tumors, and to study the potential direct or indirect mechanism." (PMID 35581573, 2022). "A large variation in MTHFD2 expression was noted in both tumor and mucosa which indicates that the gene might be useful as a prognostic marker." (PMID 36612253, 2022). "Furthermore, we will research the anti-tumor work of the MTHFD2 inhibitors to find a selective target for immunotherapy." (PMID 35581573, 2022). "Interestingly, MTHFD2 was highly expressed in tumor samples compared with normal brain tissues, suggesting an attractive target for therapeutic intervention." (PMID 33468252, 2021). "Therefore, this study uncover a role of MTHFD2 in tumor immune evasion, which elicits a powerful target in tumor immunotherapy." (PMID 33782411, 2021). "Interestingly, the highest levels of MTHFD2 expression were also found in tumor cells surrounding necrotic and acellular regions, highlighting cells of what is referred to as the pseudopalisading necrosis." (PMID 33468252, 2021). "In this study, we screened the corresponding functional role of metabolic genes from the perspective of tumor cells, and demonstrated that MTHFD2, an embryo- and tumor-specific folate cycle enzyme, could be induced by IFN-γ." (PMID 33782411, 2021). "In this study, we focused only on the PD-L1 expression to explore the functional role of MTHFD2 in tumor immunity, however, we have shown unequivocally that MTHFD2 plays an important role in global protein O-GlcNAcylation, which is known to fundamentally regulate various cellular behaviors." (PMID 33782411, 2021). "Altogether, these results suggest that MTHFD2 knockdown may inhibit cell proliferation and tumour growth via regulating cell cycle‐related genes." (PMID 31778025, 2020). "MTHFD2 is an enzyme that is required for tumor cell survival." (PMID 32111066, 2020).
tumor (continued). "Besides, though injected cells at same concentration (5×105) potentially formed tumors in all mice, the tumor size of vector control was significantly larger compared to MTHFD2-knockdown groups." (PMID 32759461, 2020). "While treatment with ionizing radiation did not significantly alter the morphology of either scRNA or MTHFD2 KD rSCC-61 tumors, treatment with β-lap caused suppression of tumor vascularization in both scRNA and MTHFD2 KD rSCC-61 tumors." (PMID 33262939, 2020). "Indeed, the in vitro and in vivo data show statistically significant suppression of clonogenic survival and tumor growth for rSCC-61 cells depleted of MTHFD2, and radiation sensitizing effects of either MTHFD2 knockdown or β-lap treatment." (PMID 33262939, 2020). "They further demonstrated that SOX7-repressed MTHFD2 could contribute to SOX7-mediated tumor suppression." (PMID 32411609, 2020). "In the groups receiving combined radiation and β-lap treatment, there was more extensive necrosis occurring in the central and peripheral areas of scRNA rSCC-61 tumors, and this was increased in MTHFD2 KD rSCC-61 tumors showing large centralized and peripheral necrosis in the entire tumor." (PMID 33262939, 2020). "The staining score of MTHFD2 is calculated for each tumor sample." (PMID 32933024, 2020). "Furthermore, MTHFD2 suppression reduced tumor growth and significantly inhibited lung metastasis in CRC cell-derived xenograft mouse model." (PMID 32411609, 2020). "In addition, for the TCGA HNSCC cohort, upregulation of MTHFD2 was positively correlated with positive lymph node metastasis and advanced tumor grade." (PMID 32933024, 2020). "Upregulation of MTHFD2 might result in increased NK cells resting and decreased NK cells activated, suggesting that MTHFD2 might exert its tumor promoting by affecting the activities of NK cells." (PMID 32933024, 2020). "Knockdown of MTHFD2 greatly inhibited tumorigenesis, as well as the tumor-initiating activity." (PMID 30532069, 2019). "Among these four genes, we determined that SOX7-activated SPRY1 and SLIT2, and SOX7-repressed TRIB3 and MTHFD2 could all differentially contribute to SOX7-mediated tumor suppression." (PMID 29757932, 2018). "A meta-analysis of gene expression data showed that MTHFD2 was one of the most consistently overexpressed mRNAs genome-wide across 19 different tumor types, and the MTHFD2 protein is specifically expressed in transformed cells but not the stroma surrounding the tumours." (PMID 26461067, 2015). "In line with this assumption, by using a xenograft tumor model, we found that the xenograft tumor growth induced by MTR loss and MTHFD2 overexpression could be abrogated by administering the serine metabolism inhibitor NCT503 (which targets the key serine metabolism enzyme PHGDH46)." (PMID 39039072, 2024). "Other studies suggest that MTHFD2 might drive tumor development by regulating the cell cycle." (PMID 40604332, 2024). "Apart from their established roles in tumor treatment, these compounds possess inherent attributes that could facilitate their utilization as effective carriers for delivering radiotracers to solid tumors characterized by heightened MTHFD2 expression." (PMID 38794278, 2024). "However, for the other RCC subtypes, the MTHFD2 may be an important trigger of metabolic disorders, contributing to an aggressive tumor behavior." (PMID 38422037, 2024). "In addition, studies have reported the role of MTHFD2 in tumor immune evasion." (PMID 37704698, 2023). "Therefore, MTHFD2 has been widely recognized as a potential therapeutic target for tumor treatment." (PMID 36051358, 2022). "Therefore, we tried to answer an important question that whether specific inhibition of MTHFD2 function by siRNA or a chemical compound can improve anti-tumor sensitivities induced by pemetrexed in LUAD." (PMID 35790743, 2022).
tumor (continued). "Importantly, we discovered that the methylenetetrahydrofolate dehydrogenase 2 (MTHFD2), a key enzyme in the transformation of folate metabolites, was markedly upregulated in tumor cells from solid LUADs, along with the enhancement of folate biosynthesis and one-carbon pool by folate." (PMID 36138435, 2022). "It remains unclear whether MTHFR and MTHFD2 are involved in tumor progression by regulating SAM." (PMID 33168819, 2020). "Our data suggest that MTHFD2 inhibition might also attenuate tumor angiogenesis." (PMID 29895827, 2018). "Thus, we wanted to determine whether ectopic expression of TRIB3 or MTHFD2 could counteract the tumor suppressive activity of SOX7." (PMID 29757932, 2018). "For group 2, it included ECOG performance status, ABCC3 expression, tumor differentiation, percentage of tumor epithelial cells in specimen, PCFT expression, and MTHFD2 expression." (PMID 40357991, 2025). "ABCC3, RFC‐1, PCFT, MFT, MTHFD2, and TYMS expression was determined by qPCR and related to tumor response and 3‐year progression‐free survival (PFS)." (PMID 40357991, 2025). "We used MTHFD2-knockdown NCI-H929 and OPM2 cells to construct MM mouse xenograft subcutaneous tumor model." (PMID 40280919, 2025). "We utilized the CCK-8 assay to investigate how alterations in MTHFD2, TYMS, and MTR affect tumor cell growth." (PMID 39039072, 2024). "More importantly, we found that DS18561882, a substrate-based inhibitor of MTHFD2, effectively attenuates MTHFD2-mediated NADPH production and tumor growth." (PMID 38723197, 2024). "For this purpose, we transfected the MTHFD2, TYMS, and MTR overexpression or knockdown vectors into the PRKDC-overexpressing HMCB cell line (PRKDC-OE-HMCB), respectively, and exanimated the tumor cell proliferation rates." (PMID 39039072, 2024). "In summary, our results strongly point to the relevant role of MTHFD2 expression in RCC, with significant implications for the prognosis and tumor aggressiveness." (PMID 38422037, 2024). "We further evaluated the impacts of MTHFD2, TYMS, and MTR on tumor cell proliferation under PRKDC overexpression conditions." (PMID 39039072, 2024). "Studies have shown that mitochondrial enzymes involved in the one-carbon pathway, namely SHMT2, MTHFD2, and MTHFD1L, affect the proliferation rate of tumor cells." (PMID 38881906, 2024). "The results revealed that compared to HMCB with MTHFD2-OE or TYMS-OE, PRKDC-OE cells that overexpressed with MTHFD2 or TYMS showed significantly elevated tumor cell proliferation." (PMID 39039072, 2024). "We found that mitochondrial SHMT2 and MTHFD2 negatively correlated with TDS, and that both genes were consistently related to tumor size and other aggressive clinico-pathological factors." (PMID 38331894, 2024). "MTHFD2, an enzyme responsible for mitochondrial NADPH production, is essential for overcoming oxidative stress and maintaining redox homeostasis in tumor cells." (PMID 37608254, 2023). "Similar to previous studies, SPP1, MTHFD2, TRIP13, MKI67, MMP9, and KLF4 were some of the most clinically valuable tumor markers, especially in CC and EC." (PMID 34834529, 2021). "Immunoblot analysis of lysates obtained from surgical samples of 6 GBM patients confirmed increase of MTHFD2 and SHMT2 expression in tumor tissues relative to normal brain tissues." (PMID 33468252, 2021). "MTHFD2 promoted the translation of HIF-2α by m6A methylation of HIF-2α mRNA, which results in promoting metabolic reprograming and tumor growth." (PMID 32933024, 2020). "In our study, we revealed that MTHFD2 is a novel substrates of SIRT3, which results in keep MTHFD2 enzyme activity and NADPH production in tumor cells." (PMID 32811824, 2020). "To further investigate the impacts of MTHFD2 and PAICS on tumor aggressiveness, we analyzed the relationship of MTHFD2 and PAICS expressions with tumor stages (INSS)." (PMID 31624245, 2019).